KRT16P2 (keratin 16 pseudogene 2)
Gene: Transcribed unprocessed pseudogene on chromosome 17 (16,829,999 to 16,832,753, reverse strand). Ensembl gene ENSG00000227300.
Diseases named in the same sentence as KRT16P2 in open-access papers:
KRT16P2 is named in the same sentence as 2 diseases in open-access papers, as found by Europe PMC text mining. Sharing a sentence is not in itself a finding about the gene and the disease. The quoted sentences say what the papers report.
malignant glioma (1 paper, 2022). A grade III or grade IV glioma arising from the central nervous system. "The eleven genes within the circadian rhythm pathway (AC020907.1, Y_RNA, TMEM72‐AS1, KRT16P2, DLX6‐AS1, AP002414.1, hsa‐miR‐424, TBPL1, NPAS2, CRY2, and ETNK1) were used to construct a model to evaluate the importance of these genes in malignant glioma." (PMID 35194922, 2022). "Since all three pathways act through AC020907.1, Y_RNA, TMEM72‐AS1, KRT16P2, DLX6‐AS1, AP002414.1, hsa‐miR‐424, TBPL1, NPAS2, and CRY2, these genes could serve as potential therapeutic targets for malignant glioma." (PMID 35194922, 2022). "Knockdown of hsa‐miR‐424 or overexpression of AC020907.1, Y_RNA, TMEM72‐AS1, KRT16P2, DLX6‐AS1, AP002414.1, and TBPL1 could regulate these three pathways to suppress malignant glioma tumorigenesis and progression." (PMID 35194922, 2022). "Fourteen genes within the tumour immune microenvironment pathway (AC020907.1, Y_RNA, TMEM72‐AS1, KRT16P2, DLX6‐AS1, AP002414.1, hsa‐miR‐424, TBPL1, NPAS2, CRY2, VPS33B, CT62, DPY19L2P1, and KCNH1‐IT1) were used to construct a model to evaluate the importance of these genes in malignant glioma." (PMID 35194922, 2022). "Fourteen genes within the cellular senescence pathway (AC020907.1, Y_RNA, TMEM72‐AS1, KRT16P2, DLX6‐AS1, AP002414.1, hsa‐miR‐424, TBPL1, NPAS2, CRY2, C9ORF40, AL136115.1, AC102941.1, and AC008738.2) were used to construct a model to evaluate the importance of these genes in malignant glioma." (PMID 35194922, 2022).
KRT16P2 also shares sentences with these, for which no sentence is quoted: tumour (1 paper).